CCL2 (C-C motif chemokine ligand 2)
Diseases named in the same sentence as CCL2 in open-access papers (continued):
Sharing a sentence is not in itself a finding about the gene and the disease.
Hepatitis (33 papers, 2013 to 2025). Inflammation of the liver. "Ovariectomized mice fed high fat diets display worse hepatitis than their intact counterparts and this exacerbation of disease is associated with increased liver expression of CCL2." (PMID 23762326, 2013). "Immature neutrophils circulating in advanced MASH patients also expressed an array of pro-inflammatory chemokines that can aggravate and perpetuate liver inflammation, such as CCL2, CCL3, CCL5, CXCL1, and XCL2." (PMID 38791066, 2024). "Ionizing calcium-binding adapter molecule 1 (Iba-1) immunostaining and Azan staining showed that the HFD-challenged Aα4KO mice developed liver inflammation and fibrosis, with elevated IL-1β, CCL2, and TGF-β1 mRNA levels." (PMID 36241662, 2022). "Together they promote the development of non‐alcoholic steatohepatitis (NASH) characterized by liver inflammation and activated inflammatory cytokine signaling pathways stimulated by TNF‐α, IL‐1β, KC/CXCL1, MCP1/CCL2, and others." (PMID 35830259, 2022). "The liver transcriptional expressions of CXCL1, CXCL2, CXCL3, CXCL5, CCL2, and CCL6 significantly increased in WT and IL-33 KO mice during L2-MHV3-induced hepatitis compared to those in control PBS-injected mice as soon as 48 h PI and at 72 h PI." (PMID 28607531, 2017). "Additionally, FGL2 upregulates the expression of C-C motif chemokine ligand 2 (CCL2), IL-1β, IL-6, and TNF-α, promoting the differentiation of macrophages into M1-like pro-inflammatory macrophages and exacerbating liver inflammation and fibrosis." (PMID 38816776, 2024). "Previous work by others demonstrated that deficiency of CCL2, a chemokine ligand of CCR2, did not prevent hepatitis in a methionine-choline deficient (MCD) mouse model of NASH." (PMID 23762326, 2013). "In addition, in one mouse model of MASLD, SB reduced hepatitis activity according to the NAS scale, production in the liver of TNF-α, IL-1β, interferon-γ, and IL-10 as well as the inflammatory cell chemoattractant CCL-2 and macrophage (Kupffer cells) biomarker F4/80." (PMID 39203520, 2024).
Hypercholesterolemia (33 papers, 2012 to 2025). An increased concentration of cholesterol in the blood. "The LLV and CCL2/MCP‐1 interaction was borderline significant, while the interaction between LLV and CD163 was statistically significant in the association with hypercholesterolemia." (PMID 39189824, 2024). "Our study is the first to show the long-term effects of purified anthocyanins on CXCL8 and CCL2 in Chinese individuals with hypercholesterolemia." (PMID 27933092, 2016). "In addition to hypercholesterolemia, chemotactic cytokines (chemokines) can further increase monocytes recruitment to the plaque; for instance, CCL2/MCP-1 cytokine can bind to CCR2 receptor on classical monocytes and induce their migration to the plaque." (PMID 39528464, 2024). "27-Hydroxycholesterol (27OHChol), an oxysterol elevated with hypercholesterolemia, enhanced production of CCL2, known as MCP1, chemokine from monocytes/macrophages and migration of the monocytic cells, but the CCL2 production and the cell migration were reduced by treatment with dexamethasone." (PMID 29236764, 2017). "LDL-C is capable of stimulating the overexpression of monocyte ligand CCL2, thus providing a link between upregulation for CCR2 receptors and hypercholesterolemia." (PMID 40020285, 2025). "Hypercholesterolemia is often accompanied by persistent inflammation, endothelial cell activation and secretion of chemokines such as CCL2/MCP-1, CX3CL1, and CCL5." (PMID 35399657, 2022). "In hypercholesterolemia, surface-adherent platelets express CXCL8 or CCL2 to recruit leukocytes, which adhere to the denuded artery and contribute to neointimal lesion formation." (PMID 27933092, 2016). "Emerging evidence indicates that the plasma levels of some platelet chemokines, such as CXCL4, CCL5, CXCL5, CXCL1, CCL2 and CXCL8, are increased in hypercholesterolemia." (PMID 27933092, 2016).
leukemia (33 papers, 2010 to 2026). A malignant (clonal) hematologic disorder, involving hematopoietic stem cells and characterized by the presence of primitive or atypical myeloid or lymphoid cells in the bone marrow and the blood. "The roles of C-X-C motif ligand 1 (Cxcl1) and C-C motif chemokine ligand 2 (Ccl2) in the development of various cancers, including leukemia, have been well documented." (PMID 41550719, 2026). "Induces apoptosis in leukemia cells by activating caspase-3; reduces chemokines (CCL2, CCL5), promoting apoptosis and cytokine regulation." (PMID 40003268, 2025). "The pro-inflammatory genes IL-1β, IL-8, CXCL1, CXCL2, CXCL3, and CCL2 were the most upregulated in MSCs co-cultured with AML leukaemia cells." (PMID 35629139, 2022). "hIL-17 and hTNF-α synergistically or additively induced CXCL8 and CCL2 expression and consequently promoted primary human neutrophil and human leukemia monocytic cell migration, respectively." (PMID 35844613, 2022). "ILK can also be activated in leukemic cells, activating a feedback loop involving ILK/NF-κB, ending with CCL2 production and promoting leukaemia progression." (PMID 35629139, 2022). "POSTN, in turn, increases the expression of CCL2 by leukemic cells and promotes leukemia cell proliferation and adhesion to BM-MSCs through the integrin-ILK-NF-κB signaling pathway." (PMID 35884364, 2022). "Seeding and growth of different B-ALL cell lines in this leukemia BM niche model showed a progressive production of chemokines such as CCL2 and pro-inflammatory cytokines, including IL-6 and CXCL8." (PMID 33922612, 2021). "In a recent study, POSTN was shown to promote the progression of B-cell acute lymphoblastic leukemia (B-ALL) by regulating the expression of monocyte chemoattractant protein 1 (MCP-1 or CCL2) in leukemia cells." (PMID 34513869, 2021). "Furthermore, as already demonstrated in the context of colon cancer, C5a could support local chronic inflammation and hamper antitumor T-cell responses by recruiting, in concert with CCL2, leukemia-associated macrophages and promoting their polarization to a M2-like phenotype." (PMID 33922612, 2021). "Ex vivo experiments from different research groups indicate that leukemia stimulation of primary BM-MSCs is able to specifically upregulate the expression of CCL2, CXCL10, CCL22, CXCL8, and CXCL1." (PMID 33922612, 2021). "Both CXCR4/SDF-1 and VLA-4/VCAM1 axes are involved in leukemia protection but little is known about the role of CCL2/CCR2 in AML biology and protection against chemotherapy." (PMID 28045930, 2017). "BMSCs co-cultured with leukemia cells up-regulated a number of proinflammatory genes including IL-17 signaling-related genes and IL-8 and CCL2 levels were increased in co-culture supernatants." (PMID 24304929, 2013). "To confirm the increased levels of CCL2 and IL-8 in the supernatants from BMSCs co-cultured with leukemia cells at 48 h, we measured the levels of the two cytokines using ELISA assays." (PMID 24304929, 2013). "Further analyses of circulating cytokine levels in these leukemia patient plasma samples via Luminex multiplex assay found a correlation between sSig15 and the cytokines MCP-1/CCL2 and IL6, which have been demonstrated to support the formation of the proleukemic bone marrow microenvironment." (PMID 37465593, 2023). "Also, it was found that leukemia cell-derived CCL2 activates STAT3 to increase periostin expression in bone marrow-derived cells (BMDCs)." (PMID 36224629, 2022). "However, the levels of CCL2 and IL-8 were greater in supernatants from BMSCs co-cultured with leukemia cells, but the results were variable among BMSCs from different subjects." (PMID 24304929, 2013). "Furthermore, M-CSF, macrophage migration inhibitory factor (MIF), IL-8, and CCL2 may promote a protumoral MΦ polarization contributing to forming a protective niche for leukemia stem cells." (PMID 34771453, 2021).
leukemia (continued). "Thus, besides a potential therapeutic use in leukemia vaccination approaches via its strong up-regulatory effect on CCL2 expression which is known to raise immunosurveillance, miR-511 may prove useful in differentiation treatment strategies." (PMID 26762252, 2016). "ARC upregulated IL1β in AML cells and increased the levels of CCL2, CCL4, and CXCL12 in MSCs by activating the NFκB pathway, thereby promoting the migration and adhesion of leukemia cells to MSCs." (PMID 39351758, 2024). "We discovered that miR-552-3p was down-regulated significantly in human hepatic stellate cell line (LX-2), while was up-regulated in human leukemia monocytic cell line (THP-1) in response to TGF-β1, CCL2 and LPS stimulation." (PMID 37496991, 2023). "By examining IL-17 signaling-related genes, IL-8, CCL2 levels, mTOR signaling and EIF2 signaling pathways genes, it is confirmed that BMSCs and leukemia cells both contribute to the creation of a competitive niche more favorable for leukemia stem cells." (PMID 33146708, 2020). "Collectively, these results suggest that like CXCR4/CXCL12, the CCR2/CCL2 and CCR5/CCL4 receptor/chemokine axes contribute to leukemia-MSC interactions, and that the chemokines expressed by MSCs are regulated, at least in part, by ARC in AML cells." (PMID 26956049, 2016). "Specifically, CCL2 is one of the most highly expressed chemokines in BM-derived MSCs, and its expression is regulated through ARC in MSCs and by ARC-induced IL1β from leukemia cells." (PMID 26956049, 2016). "We identify that, in addition to the well-known CXCR4/CXCL12 axis, CCR2/CCL2 and CCR5/CCL4 also drive leukemia/stromal interactions." (PMID 26956049, 2016). "This is the first report on the important role of ARC in the regulation of the CCR2/CCL2 and CCR5/CCL4 axes in leukemia and stromal cells." (PMID 26956049, 2016). "The level of CCL2 was measurable only in supernatants from BMSC003, BMSC002 and BMSC006 co-cultured with TF-1 and K562 leukemia cells and in the supernatant from BMSC006 co-cultured with TF-1α." (PMID 24304929, 2013). "We found that CXCL1, CXCL6, TEP1, IL8, CCL2 and PTGS2 genes were the most up-regulated genes in BMSCs co-cultured in the direct contact with leukemia cells." (PMID 24304929, 2013). "The RT-PCR results confirmed the greater expression of CCL2, ICAM1, IL8 and IL1B in BMSCs co-cultured with leukemia cells compared with BMSC mono-cultures." (PMID 24304929, 2013). "Finally, our results suggest that CCL2/CCR2 axis may have a role in a subset of AML patients, especially in monocytoid AML, which represent the leukemias with higher CCR2 expression." (PMID 28045930, 2017).
lung disease (33 papers, 2005 to 2025). "CCL2 alone is associated with severity of TB, possibly due to increased systemic inflammation found in severe disseminated TB or due to increased monocyte infiltration to lung parenchyma in pulmonary disease." (PMID 20041183, 2009). "Lung diseases can be further aggravated by inflammatory cytokines such as CCL2 and interleukin (IL)-6." (PMID 38004123, 2023). "From the cytokine profile analysis, MCP-1/CCL2 and SDF-1α were associated with RA-ILD, and IL-18 levels were associated with RA-ILD and more prominent progressed lung disease." (PMID 37833957, 2023). "The reasons for these disparate roles of CCL2 in lung disease remain to be elucidated and require further study." (PMID 24499286, 2014). "We also observed greater CCL2 activation in pulmonary tuberculosis as compared with extra-pulmonary disease in response to both BCG and LPS stimulation." (PMID 16001981, 2005). "Some cytokines, for example, MCP-1/CCL2 and SDF-1 alpha were associated with the diagnosis of RA-ILD, and IL-18 levels were associated with a diagnosis of RA-ILD and a more marked progression of lung disease." (PMID 37047772, 2023). "We have reported that IFN-γ -874 Thi allele was associated with less severe pulmonary disease but not with severe pulmonary or extra pulmonary tuberculosis while CCL-2 responses show the opposite trend and are higher in severe disease compared to less severe disease." (PMID 21991356, 2011). "Recently elevated levels of CC chemokines MCP-1(CCL2), MIP-1α,(CCL3), MIP-1β and (CCL4) and MIP-3α (CCL20) were reported in BALF of young children with CF with little apparent lung disease or infection." (PMID 24216293, 2013). "As for the cytokine profile, patients with RA-ILD and the progression of lung disease had higher values of IL-1 alpha, IL-18, and MCP-1/CCL2 than those whose disease did not progress." (PMID 37047772, 2023). "Among them, monocyte chemoattractant protein-1 (MCP-1 or CCL2) and macrophage inflammatory protein-1β (MIP1β or CCL4) may play a role in SSc, as the overexpression of these chemokines has been detected in SSc-related lung disease." (PMID 19615053, 2009). "Only future prospective studies will be able to determine if the levels of CCL2 and CCL5 are predictive of outcomes and if the combined inhibition of these receptor(s)/ligand(s) interactions may lead to an inhibition of progression or even reversal of this lung disease." (PMID 21463523, 2011).
type 1 diabetes (33 papers, 2006 to 2025). "CCL5 and CCL2 chemokines were shown to be significantly elevated in the type 1 diabetes group vs. controls." (PMID 38937380, 2024). "A similar behavior was found in a type 1 diabetes model where the monocytes were less strongly attracted by MCP-1 (CCL2) and MIP-1α (CCL3) but stronger to MIP-3β (CCL19)." (PMID 34502120, 2021). "Notably, CCL2 was uniquely enriched in glycosphingolipid biosynthesis and type I diabetes mellitus pathways, indicating its potential role in bridging metabolic and inflammatory processes." (PMID 40969366, 2025). "Furthermore, high maternal levels of circulating inflammatory cytokines (IFN-γ, IL-1β, CCL2, and CCL4) during pregnancy have been associated with increased risk of type 1 diabetes in the offspring." (PMID 35693790, 2022). "In vitro treatment with 1,25(OH)2D3 reduced proinflammatory cytokines (IL-6, CCL-2, IL-23A, IL-15) whereas anti-inflammatory cytokines (IL-10 and PD-L1) rose both in APS-type 1 diabetes and APS-Addison ́s disease." (PMID 33365026, 2020).
uveitis (32 papers, 2009 to 2024). An inflammatory process affecting a part of or the entire uvea. "Notably, our previous induced uveitis rodent studies demonstrated SOCS1-KIR mediated decreases in the chemokines CCL2, CCL20 and CXCL9, in addition to the chemokine receptors CCR2, CCR4, CCR6 and CXCR35,25." (PMID 35505065, 2022). "Others showed that the frequency of the T allele of MCP-1 63555 (rs1024610/CCL2) was significantly associated with idiopathic anterior uveitis in Caucasian patients, which could not be shown in the uveitis entities we studied." (PMID 28589131, 2017).
allergic asthma (31 papers, 2004 to 2025). A asthma with a basis in a pathological type I hypersensitivity reaction. "We found that T-bet-/- mice exposed to NiNPs had exaggerated airway mucous cell metaplasia, higher levels of mucin gene mRNAs, and increased levels of IL-13 and CCL2, two cytokines implicated in allergic asthma." (PMID 24499286, 2014). "In allergic asthma, Cloots and coworkers showed that mice genetically deficient for Arg1 displayed a reduction in Il4, Il5, Il13, Ccl2, and Ccl11, all Th2-related genes, suggesting that Arg1 may regulate type 2 inflammation." (PMID 34834178, 2021). "The levels of MCP-1 (CCl2) were significantly higher in HP patients than in sarcoidosis (p < 0.0001), non-allergic asthma (p = 0.008), and EGPA (p = 0.03) patients." (PMID 40725075, 2025). "More interestingly, blockade of CCL2/CCR2 signaling provides protective immunity in murine models of OVA‐induced allergic asthma." (PMID 39988712, 2025). "Inhibition of CCL2 pathway was shown to prevent a Th2 response in allergic asthma." (PMID 35163137, 2022). "It was previously shown that CCL2 recruits macrophages to sites of inflammation after allergen exposure, and that the blocking of CCL2 signaling pathway prevents Th2 inflammatory response in allergic asthma." (PMID 34299258, 2021). "Also, chemerin is involved in inflammation by activating p38 MAPK pathway in renal injury and inhibits CCL2 secretion in allergic asthma, leading to recruitment of inflammatory dendritic cells." (PMID 34210352, 2021). "Therefore, the authors studied the effects of anti-CCL2 antibodies and CCR2 antagonist on the induction of allergic asthma, the levels of IL-17 and the frequencies of CCL2+ Th17 and Tc17 cells, as well as lung inflammation." (PMID 26953825, 2016). "Monocyte-derived Aφs recruited in response to airway epithelial-derived monocyte chemoattractant protein 1/CCL2, are involved in airway inflammation and remodeling in allergic asthma." (PMID 30108592, 2018). "Elevated levels of CCL2 have been found in the BALF and bronchial tissue of individuals with allergic asthma." (PMID 24499286, 2014). "In the pathogenesis of allergic asthma (without hyperoxia), allergens, pollutants, and infectious agents induce GATA-3 transcription factor activation and chemokine CCL2 (MCP-1) expression which promote T cell differentiation toward TH2 and activation of macrophages M2." (PMID 26417446, 2015).
glomerulosclerosis (31 papers, 2013 to 2025). A hardening of the kidney glomerulus caused by scarring of the blood vessels. "CCL2, a ligand for C-C chemokine, contributes to glomerulosclerosis and mediates macrophage-associated inflammation." (PMID 41438111, 2025). "Accordingly, in an animal model of nephrectomy in db/db mice, increased H3K4me2 renal levels were associated with renal function loss and glomerulosclerosis, and this effect was diminished by treatment with MCP-1/CCL2 antagonist (Spiegelmer mNOX-E36)." (PMID 30647531, 2018). "Standard LN therapies, like mycophenolate and rapamycin, improve glomerular sclerosis by downregulating CCL2 and reducing fibrosis-related proteins." (PMID 39850880, 2024). "Under diabetic conditions, CCL2 expression is upregulated in various kidney cell lines, leading to proliferation of mesangial cells, glomerulosclerosis, and kidney fibrosis." (PMID 35706905, 2022). "Similarly, in 125 patients with active lupus nephritis (LN), urinary CCL2 levels were positively correlated with interstitial inflammation, glomerulosclerosis, interstitial fibrosis, and tubular atrophy based on kidney biopsies." (PMID 39850880, 2024). "CCL2 activates CCR2 on proinflammatory monocytes/macrophages and draws them into inflamed glomeruli, where myeloid cells play a vital role in podocyte injury and glomerulosclerosis." (PMID 34369383, 2021).